SOD1 (superoxide dismutase 1)
Diseases named in the same sentence as SOD1 in open-access papers (continued):
Sharing a sentence is not in itself a finding about the gene and the disease.
infection (continued). "The genome of the pathogenic fungus Fusarium graminearum is known to contain five SOD genes, and the cytoplasmic Cu–Zn superoxide dismutase (SOD1) has been deemed essential to fungal growth and successful infection of wheat heads." (PMID 33439999, 2021). "We observed an increased SOD1 content in infected animals with 30 days of infection, but in later periods SOD1 was increased in both the control and infected groups." (PMID 34303703, 2021). "Infection with H5N1 decreases SOD1 promoter activity, whereas the overexpression of SOD1 disrupts H5N1 virus replication in A549 cells." (PMID 32689931, 2020). "In a cell culture model, during the first hours after infection, SOD1, SOD2, glutathione S-transferase (GST), CAT, and GPx are induced." (PMID 33381273, 2020). "Modulated SOD-1 expression and activity has also been observed from infection by respiratory syncytial virus and influenza A virus." (PMID 33081049, 2020). "On the other hand, higher SOD activity seems to be useful to combat the excess free radicals produced during the infection, resulting in a lower expression of the SOD1 gene." (PMID 31297194, 2019). "In mouse peritoneal and human macrophages linages, infection by L. amazonensis leads to the increase of SOD1 expression in a PKR/Nrf2-dependent manner." (PMID 31998662, 2019). "Intracranial infection with ATCV-1 significantly accelerated the progression of ALS-like symptoms in the SOD1-transgenic mice." (PMID 31878033, 2019). "In the blood, SOD1-5′AS expression is enriched in dendritic cells, mast cells, and monocyte-derived macrophages upon LPS treatment and infection with influenza virus." (PMID 30610612, 2019). "Lungs samples were harvested at day 1 post-infection to assess mRNA levels of catalase, Cu/Zn-superoxide dismutase (SOD1), CSE, CBS, and 3-MST." (PMID 29740449, 2018). "A transient activation has been reported during the first several hours post infection in lung carcinoma cells in vitro, as exemplified by induction of SOD1, SOD2, GST (glutathione S-transferase), catalase, and GPx." (PMID 30049972, 2018). "Infection with ST resulted in substantial reduction in the expression of SOD-1, SOD-2, catalase and GADD45A, perhaps to allow ROS levels to build-up to control the pathogen." (PMID 27599659, 2016). "At 8wks post infection, the most prominent genes which were significantly up-regulated in the liver tissue encode MCM, NDUF1, AACS, P450RAI-2, DARS, MRPL39, SOD1, associated with mitochondrial respiration and aerobic metabolism." (PMID 27467147, 2016). "In this infection model, the early production of type I IFN causes tissue pathology due to the downregulation of superoxide dismutase 1 (Sod1) in the liver." (PMID 28066439, 2016). "This was associated with increased expression of cell-death-associated genes and more cleaved caspase-3 positive hepatocytes in the liver at 16 hr after infection, indicating the rapid activation of apoptotic pathways in infected Sod1−/− mice." (PMID 26588782, 2015). "More than 100 days after infection, Sod1−/− mice showed recovered body weight compared to WT mice and comparable residual viral RNA in the liver." (PMID 26588782, 2015). "In the early phase of infection, we found a more pronounced upregulation of interferon-stimulated genes in Sod1−/− compared to WT mice." (PMID 26588782, 2015). "LCMV infection, however, led to elevated staining of 8-oxoG in hepatocytes of Sod1−/− mice at 16 hr after infection, confirming increased virus-induced oxidative damage in the liver." (PMID 26588782, 2015). "Thirty days after infection with LCMV strain clone 13 Sod1−/− mice showed fibrotic processes in the liver tissue as indicated by increased Col1a1 mRNA expression." (PMID 26588782, 2015). "We found comparable numbers of infiltrating CD8+ and CD4+ T cells in the liver tissue of infected Sod1−/− and WT mice at 24 hr after infection." (PMID 26588782, 2015).
infection (continued). "SOD1 knockdown by lenti-RNAi-SOD1 infection in myocardial cells resulted in upregulation of ROS levels to approximately 1.4-fold (P < 0.05)." (PMID 25816284, 2015). "Together, this indicated that Sod1−/− mice exhibited increased fibrotic changes during the late phase of infection compared to WT mice." (PMID 26588782, 2015). "This coincided with our observation that infection with LCMV resulted in a downregulation of SOD1 expression at the RNA and protein level." (PMID 26588782, 2015). "Yet, we found increased levels of 8-oxoguanine (8-oxoG), a marker for oxidative damage, in the liver tissue of Sod1−/− mice at 123 days after infection." (PMID 26588782, 2015). "Compared to mice receiving artesunate alone, addition of rosiglitazone adjunctive therapy resulted in significantly increased levels of SOD-1 and catalase expression and full recovery to pre-infection levels by day 9 post-infection." (PMID 24603727, 2014). "Increasing concentrations of NAC strongly increased SOD1 protein levels in infected cells thus demonstrating that SOD1 down regulation was the result of increasing ROS levels after MP12 infection." (PMID 21655261, 2011). "While there are temporal differences in the down regulation of SOD1 among multiple cell types, there is a consistent down regulation at the early time points (24 h post infection) reinforcing this to be an early host event due to infection." (PMID 21655261, 2011). "One possible down stream effect of an increase in ROS following infection is a consistent reduction in the levels of SOD1, the most abundant cytoplasmic cellular antioxidant enzyme." (PMID 21655261, 2011). "Whole cell extracts were obtained at 0, 24, 30, 48 and 72 h post infection and were analyzed by western blot analysis for changes in SOD1." (PMID 21655261, 2011). "We found that similar to what we observed with the HSAECs, HepG2s showed lowered SOD1 levels at earlier time points following infection (red circles)." (PMID 21655261, 2011). "For discrimination of mild infection, elevated SOD-1 levels showed greater sensitivity than TNF-alpha (76% vs. 30% respectively; p<0.0001), with higher specificity (100% vs. 97%; p<0.0001)." (PMID 20386593, 2010). "Adenoviral expression of SOD1 dramatically increased the levels of SOD1 in BAEC compared with GFP infection." (PMID 21079763, 2010). "For discrimination of mild infection, the use of SOD-1 improves the correct case detection by more than 45% compared with the use of TNF-alpha, in addition to being a better identifier of negative cases." (PMID 20386593, 2010). "We also assessed the possibility of estimating threshold levels of TNF-alpha and SOD-1 to discriminate between asymptomatic and symptomatic infection." (PMID 20386593, 2010). "Our results show that I-17 partially prevented the upregulation of Nrf2 and SOD1, which may contribute to infection reduction." (PMID 38392842, 2024). "Infection of SOD1-G93A mice with active ATCV-1 significantly accelerated onset of motor loss, as measured by tail paralysis, hind limb tucking, righting reflex, and latency to fall in a hanging cage-lid test, but did not significantly affect mortality when compared to saline-treated transgenics." (PMID 35280283, 2022). "SOD1 reduces the Leishmania oxidative stress and may promote the parasite survival and affect the outcome of the infection." (PMID 33898331, 2021). "Indeed, Sod1−/− mice treated with liposomal clodronate to deplete phagocytic cells had reduced concentrations of serum IFN-α upon infection, which was accompanied by lower concentrations of ALT." (PMID 26588782, 2015). "Upon infection Sod1−/− and WT mice showed comparable viral loads in blood, liver, and spleen and kidney, which argued against a role for SOD1 in virus control." (PMID 26588782, 2015).
infection (continued). "All the major efforts in utilizing SOD for radioprotection focus on the modification of the molecule so that it can be delivered into the cells, the methods of overexpression SOD1 intracellular including liposomal encapsulation, plasmid transfection or adenovirus-mediated infection." (PMID 24175971, 2013). "Thus, the effect of allelic variation at sod1 on resistance to infection was most important in predicting infection in the genetic background having high average resistance, and was largely irrelevant in the low-resistance genetic background." (PMID 22724037, 2012). "SOD1 can participate in both signaling and effector mechanisms, and the products of many loci may need to interact properly to sufficiently clear an infection." (PMID 22724037, 2012). "Our results demonstrated that SOD1 levels were reduced at 24 and 30 h following infection." (PMID 21655261, 2011). "We observe this reduction in SOD1 following MP12 infection in several cell types suggesting that oxidative stress could be a common phenomenon in various cells associated with RVFV infection." (PMID 21655261, 2011). "Our data demonstrates that the down regulation of SOD1 is likely to be due to post transcriptional processes and may be related to up regulation of TNFα following infection." (PMID 21655261, 2011). "Our observation that SOD1 shows a decrease at early time points following infection prompted us to ask the direct question whether infected cells experience oxidative stress at comparable time points." (PMID 21655261, 2011). "Taken together, our data suggests that an increase in TNFα level may cause down regulation of SOD1 in HSAECs and that MP12 infection causes a modest up regulation of TNFα gene transcription." (PMID 21655261, 2011). "Interestingly, SOD1 protein was present at lesion sites late in the infection." (PMID 27362522, 2016). "This seems unlikely given the association between sod1 genotype and resistance was discovered using a functional approach (e.g. knocking down H2O2 production in B. glabrata hemocytes increases their susceptibility to infection), but the functional basis of the association still needs to be proven." (PMID 22724037, 2012). "Compared with the blank group, the mRNA levels of SOD1, SOD2, and SOD3 were significantly increased on the fifth day after PR8 infection." (PMID 36829913, 2023). "In conclusion, we have established a connection between TLR4-NE, PKR activation, and gene expression of IFNs-I, IL10, SOD-1, and OASL2 upon infection of murine macrophages by L. donovani." (PMID 35154115, 2022). "infection, we found the enzyme activity of SOD and mRNA expression of SOD1 were significantly increased in the liver and bone marrow." (PMID 35923236, 2022). "For the ELISA detection of TUBA4A, SOD1 and EIF4A in serum and BALF, we only analyzed samples from 12 to 120 h post infection due to the shortage of the same batch of samples for omics detection." (PMID 34952961, 2021). "On the contrary, a single infection with RSV resulted in diminished Nrf2 and partially diminished CAT and SOD1, while expressions of NF-κB and its phosphorylated form were greatly enhanced compared to control." (PMID 32466130, 2020). "Therefore, whether SOD1 is a marker of IV infection remains uncertain." (PMID 32689931, 2020). "IV infection can decrease the production of antioxidation targets, such as HO-1 and NQO1, SOD1, GR, CAT, and GPx1 are downstream molecules of the Nrf2 pathway after IV infection." (PMID 32689931, 2020). "Infection with rhinovirus significantly induced protein levels of manganese-dependent superoxide dismutase (SOD2) and copper-zinc superoxide dismutase (SOD1) (p < 0.05)." (PMID 31849956, 2019). "In response to S. pneumoniae, there was augmented SOD1 and SOD2 mRNA expression in aged macrophages at 2 hours post infection." (PMID 30700745, 2019).
infection (continued). "It is thus conceivable that PrPC functions to maintain Cu content and regulate SOD1 through the OR region in lungs, thereby reducing ROS in IAV-infected lungs and eventually protecting them from lethal infection with IAVs." (PMID 29723291, 2018). "Enzymes related to detoxification, such as superoxide dismutases, SOD1 (PADG_07418) and SOD2 (PADG_01755) were also accumulated in P. brasiliensis yeast at 6 h post-infection." (PMID 28704618, 2017). "The reduction of SOD-1, SOD-2, catalase and GADD45A was much more pronounced in the livers of FoxO3a−/− mice following infection with ST." (PMID 27599659, 2016). "Collectively, our data provides evidence that cells experience strong oxidative stress at earlier time points following infection by MP12 virus and this contributes to SOD1 protein down regulation." (PMID 21655261, 2011). "Collectively, our data demonstrate that following exposure to ZH501 strain of RVFV, human cells undergo similar alterations in SOD1 protein levels and elicit similar responses as observed in the case of a MP12 infection." (PMID 21655261, 2011). "We exposed human lung epithelial cells to the MP12 strain of RVFV and first evaluated the levels of the two major enzymes involved in the maintenance of cellular oxidative homeostasis, SOD1 and SOD2 at multiple time points after infection." (PMID 21655261, 2011). "As expected, individuals with symptomatic infection (mild or severe) presented higher levels of both TNF-alpha and SOD-1 than those who were symptomless." (PMID 20386593, 2010). "CAT and SOD1 expression significantly increased in both WL and PC birds, regardless of the source of infection." (PMID 39066292, 2024). "Sod1 and Prdx1 were not significantly affected by infection, while interestingly Hmox1 expression was increased at 2 dpi." (PMID 37022178, 2023). "Sod1, Sod2, Cat, and Nrf2 transcripts were elevated in the E8.5 infection group only, with Hmox1 expression being predicted only by infection but not by infection day." (PMID 35312688, 2022). "Notably, SOD1 is an important interaction molecule that exists both in BALF, PBMC and serum, and participates in early and late stages of infection, followed by PRKAR1A, IARS, SNRNP200, and DHX15." (PMID 34952961, 2021). "Considering that SOD1 acts as a key scavenger to detoxify superoxide anion mainly found in the cytoplasm, we further investigated the changes in mRNA and proteins upon H5N1 challenge at different times post-infection." (PMID 26761025, 2016). "Furthermore, we infected Sod1−/− mice with a replication-defective recombinant LCMV vector (rLCMV), which is capable of only a single round of infection." (PMID 26588782, 2015). "Intriguingly, our point estimate of infection odds reduction by sod1 D, after accounting for sod1 B and RADres1 E, was quite high (3.5) but not significant (uncorrected p = 0.06)." (PMID 26372103, 2015). "Sod1−/− but not Sod2+/− or Sod3−/− mice lost more body weight compared to WT mice, which started in the early phase of infection." (PMID 26588782, 2015). "Depletion of Sod1 by RNAi from Histoplasma yeasts does not impair lung infection; the gfp-RNAi and gfp:SOD1-RNAi strains establish comparable fungal burdens in lungs throughout acute and clearing stages of infection." (PMID 22615571, 2012). "Over all, the data from multiple cell types suggest that early down regulation of SOD1 and activation of p38 MAPK may be common phenomena following infection by RVFV." (PMID 21655261, 2011). "In addition, Cu/Zn superoxide dismutase (SOD1), which can limit parasite development in Anopheles, was also upregulation during the infection." (PMID 19956592, 2009). "Overall, CMA3p20 infection of BALB/c mice caused a significant decrease in the expression of the AOE genes in the lung tissue, specifically Cat, Gstm1, and Prdx6, while it did not affect Sod1 and Prdx1." (PMID 37022178, 2023).
infection (continued). "Furthermore, the induction of IL10 and of SOD1 gene expression was also dependent on TLR3, showing that the anti-viral-type responses conveyed via PKR and TLR3 are mobilized by L. donovani to downmodulate the inflammatory response of macrophages, likely influencing infection." (PMID 35154115, 2022). "In addition, T cell receptor beta chain (Tcrb)−/−→ Sod1−/− and perforin 1 (Prf1)−/−→ Sod1−/− bone marrow chimeric mice, lacking either αβ T cells or the hematopoietically-expressed cytolytic effector protein PRF1 respectively, exhibited liver damage similar to controls upon infection." (PMID 26588782, 2015). "Neither SOD-1 nor TNF-alpha could differentiate between the infections." (PMID 20386593, 2010). "Again, Sod1−/− mice, but neither Sod2+/− nor Sod3−/− mice, showed highly elevated concentrations of ALT within the first 2 days of infection." (PMID 26588782, 2015). "Even though the main leishmanicidal effect of IFNβ on L. major-infected macrophages relates to increases in iNOS, it is possible that the induction of SOD1 by PKR helps to counterbalance the negative effect of IFNβ and iNOS, contributing to infection." (PMID 24732131, 2014).